PLXDC2 (plexin domain containing 2)
Description:
May play a role in tumor angiogenesis.
Synonyms: TEM7R; FLJ14623; PLXDC2-OT
Tractability: Antibody: UniProt predicts a signal peptide or a membrane-spanning region. PROTAC: ubiquitination databases record sites on it; its protein half-life has been measured.
Gene: Protein-coding gene on chromosome 10 (19,815,943 to 20,289,856, forward strand). Ensembl gene ENSG00000120594.
Subcellular location: Membrane
Subcellular location (Human Protein Atlas): Nuclear bodies
Gene Ontology:
Molecular function: protein binding
Cellular component: nuclear body; membrane
Genetic constraint (gnomAD): Loss-of-function variants: 33 observed, 58.31 expected, observed/expected ratio (o/e) 0.57, 90% interval 0.43 to 0.76. The upper end of that interval is the gene's LOEUF score, 0.76, which puts it in group 3 of 6, group 1 being the genes least tolerant of losing a copy. Missense variants: 590 observed, 606.94 expected, observed/expected ratio (o/e) 0.97, 90% interval 0.91 to 1.04. Synonymous variants: 221 observed, 217.23 expected, observed/expected ratio (o/e) 1.02, 90% interval 0.91 to 1.14.
Homologues: Orthologues: macaque PLXDC2 (98% identical), pig PLXDC2 (92% identical), guinea pig PLXDC2 (92% identical), mouse Plxdc2 (92% identical), rabbit PLXDC2 (88% identical), rat Plxdc2 (87% identical), chimpanzee PLXDC2 (83% identical), zebrafish plxdc2b (64% identical), zebrafish plxdc2a (52% identical), Drosophila melanogaster l(1)G0289 (32% identical), Caenorhabditis elegans pxd-1 (29% identical). Paralogues in human: PLXDC1 (48% identical).
Diseases named in the same sentence as PLXDC2 in open-access papers:
PLXDC2 is named in the same sentence as 39 diseases in open-access papers, as found by Europe PMC text mining. Sharing a sentence is not in itself a finding about the gene and the disease. The quoted sentences say what the papers report.
gastric cancer (7 papers, 2021 to 2025). A primary or metastatic malignant neoplasm involving the stomach. "Moreover, a recent report indicated that PLXDC2 was expressed in stromal cells of gastric cancer and that its crosstalk with tumor-associated macrophages could contribute to cancer biology by inducing the EMT process." (PMID 35661947, 2022). "Conversely, overexpression of PLXDC2 in stromal-associated M2 macrophages is linked to epithelial-to-mesenchymal transition (EMT) and gastric cancer progression." (PMID 39684750, 2024). "One follow-up investigation further showed that PLXDC2 is a critical gene associated with the TME, and its upregulation correlates with advanced clinical stages and predicts a shorter OS of patients with gastric cancer." (PMID 37089864, 2023). "In this study, we found that PLXDC2 was highly expressed in gastric cancer tissues, and the expression levels were positively correlated with clinicopathological features, but negatively with the patients’ outcome." (PMID 35661947, 2022). "Knockdown of PLXDC2 markedly suppressed the in vitro invasion and in vivo metastasis of gastric cancer cells, while overexpression of PLXDC2 resulted in opposite effects." (PMID 35661947, 2022). "PLXDC2 expression is related to T cell CD4 memory resting proportion within gastric cancer." (PMID 38564630, 2024). "Furthermore, PLXDC2 is associated with diverse malignant tumor behaviors, including those in human ovarian cancer, hepatocellular carcinoma (HCC), colorectal cancer and gastric cancer." (PMID 41365610, 2025). "Notably, PLXDC2 was co‐localized with cortactin, suggesting that PLXDC2 might be involved in the formation of invasive protrusions together with cortactin, as previously reported in gastric cancer." (PMID 41365610, 2025). "Collectively, our results indicate that PLXDC2 contributes to the invasion and metastasis of gastric cancer by inhibiting PTP1B to facilitate the invadopodium formation, and may serve as a potential prognostic biomarker and a therapeutic target for this disease." (PMID 35661947, 2022).
primary open-angle glaucoma (4 papers, 2012 to 2021). "It has been reported that the genetic variant near the PLXDC2 gene has an impact on the risk of primary open-angle glaucoma by increasing intraocular pressure in the Japanese population." (PMID 33995275, 2021). "Since POAG is the second most prevalent type of glaucoma in Saudi Arabia, we investigated an association between SNP rs7081455 near PLXDC2 gene and POAG or its endophenotype traits in a Saudi cohort." (PMID 30326957, 2018). "Polymorphism rs7081455 flanking PLXDC2 has been associated with primary open angle glaucoma (POAG) and its clinical phenotypes and may have a role in POAG." (PMID 30326957, 2018).
autoimmune disease (2 papers, 2020 to 2021). A disorder resulting from loss of function or tissue destruction of an organ or multiple organs, arising from humoral or cellular immune responses of the individual to their own tissue constituents. "One of them (Plexin domain-containing 2; Plxdc2) was confirmed to play an immunoregulatory role in the Hp infection, in a mouse model of inflammatory bowel disease, and potentially in other inflammatory and autoimmune diseases." (PMID 33801073, 2021). "One of them, Plexin domain containing 2 (Plxdc2), was chosen and further confirmed to have an immunoregulatory role with the potential to be used as molecular target for the development of treatments for inflammatory and autoimmune diseases." (PMID 32661418, 2020).
colitis (2 papers, 2020 to 2024). Inflammation of the colon. "Moreover, the loss of Plxdc2 significantly worsens experimental inflammatory bowel disease (IBD) caused by the DSS model of colitis, based on an exacerbated disease severity, inflammatory cytokine expression, and more severe colonic lesions in Plxdc2−/− mice." (PMID 32661418, 2020). "Plexin Domain Containing 2 (PLXDC2) deficiency in bone-marrow-derived macrophages (BMDMs) is associated with increased inflammation, as demonstrated by its role in modulating the host immune response during Helicobacter pylori infection and in chemically-induced colitis models." (PMID 39684750, 2024).
colorectal cancer (2 papers, 2021 to 2025). A primary or metastatic malignant neoplasm that affects the colon or rectum. "In human colorectal cancer, PLXDC2 expression was increased in the invasive area, suggesting that PLXDC2 may also be associated with PDAC progression." (PMID 41365610, 2025). "While the functions of PLXDC2 in some tumors have been explored and demonstrated to have potential significance in the progression and molecular targeting of cancers such as colorectal cancer, few studies have focused on the behavior of PLXDC2 in GC, and our study addressed this gap." (PMID 34124056, 2021). "As a note, we used a highly specific and low‐background anti‐PLXDC2 rabbit antibody (clone 4G3), which allowed us to specifically detect PLXDC2 expression in the tumor area of PDAC, as well as in HCC and colorectal cancers in our previous studies." (PMID 41365610, 2025). "We observed that PLXDC2 was expressed in the cytoplasm of PDAC, a pattern consistent with our previous reports on human HCC and colorectal cancer." (PMID 41365610, 2025). "Studies of PLXDC2 and its closest homolog, PLXDC1, have been conducted in cancers, including breast cancer, colorectal cancer, and typical liver cancer types." (PMID 34124056, 2021).
diabetes (2 papers, 2019 to 2021). "First, LAMA2, MLL4 and PLXDC2 are novel diagnostic markers for pre-diabetes." (PMID 33995275, 2021). "LAMA2, MLL4 and PLXDC2 may be suitable diagnostic markers for (pre-)diabetes." (PMID 33995275, 2021). "We report associations of CAD with the PLXDC2 gene and DR with the UBE2D1 gene, both of these genes may contribute to DR and CAD as part of diabetes progression by playing a role in angiogenesis and neovascularization." (PMID 31130920, 2019). "Thus, the results suggest that PLXDC2 may be a potential marker in (pre-)diabetes and its complications." (PMID 33995275, 2021). "Moreover, LAMA2, MLL4 and PLXDC2 may be worth investigating for diabetes development." (PMID 33995275, 2021). "After immunoblotting analysis of healthy patients as well as patients with pre-diabetes and brain stroke, LAMA2, MLL4, and PLXDC2 emerged as potential (pre-)diabetic markers." (PMID 33995275, 2021). "Additionally, comparison of the expression level of LAMA2, MLL4, PLXDC2, CD14, CLU, CD99 and SAA2 in sera of healthy volunteers and patients with stroke and pre-diabetes suggests that LAMA2, MLL4 and PLXDC2 have better specificity for (pre-)diabetes than CD14, CLU, CD99 and SAA2." (PMID 33995275, 2021).
hepatocellular carcinoma (2 papers, 2023 to 2025). A malignant tumor that arises from hepatocytes. "In humans, PLXDC2 has been found to be expressed in endothelial cells of the tumor stroma, neural progenitor cells, and pluripotent stem cells and in human hepatocellular carcinoma (HCC) tissues, including HCC cells, tumor vascular endothelial cells, and some infiltrating cells." (PMID 37139333, 2023).
melanoma (2 papers, 2011). A malignant, usually aggressive tumor composed of atypical, neoplastic melanocytes. "Plxdc2 (TEM7R) is strongly expressed in endothelial cells of stroma of human colorectal tumours and mouse melanoma but not of surrounding normal tissue." (PMID 21283688, 2011).
psoriasis (2 papers, 2022 to 2025). An autoimmune condition characterized by red, well-delineated plaques with silvery scales that are usually on the extensor surfaces and scalp. "A few DEPs, such as SERPINC1, SERPINF2, F2, PLXDC2, and TYMP, were also involved in regulating blood coagulation and angiogenesis, which plays an essential role in the pathogenesis and maintenance of psoriasis." (PMID 36483564, 2022).
vulvar squamous cell carcinoma (2 papers, 2018 to 2022). An invasive squamous cell carcinoma arising from the vulva. "In vulvar squamous cell carcinoma, PLXDC2 has been reported as an unfavorable prognostic marker." (PMID 35661947, 2022). "Although the roles of PLXDC2 in cancer have not been fully characterized, several studies have linked PLXDC2 to the metastasis and progression of tumors, such as breast cancer and vulvar squamous cell carcinoma." (PMID 35661947, 2022).
acute lymphoblastic leukemia (1 paper, 2011). Leukemia with an acute onset, characterized by the presence of lymphoblasts in the bone marrow and the peripheral blood. "Also, CpG islands in the Plxdc2 promoter show large methylation differences between subtypes of acute lymphoblastic leukemia and Plxdc2 is one of 40 genes whose methylation status strongly predicts prognosis." (PMID 21283688, 2011).
breast carcinoma (1 paper, 2022). "In breast cancer, elevated PLXDC2 expression at mRNA level was associated with lymph node metastasis and disease progression." (PMID 35661947, 2022).
colorectal tumour (1 paper, 2011). "In the human, mouse and chick Plxdc2 has one related gene, Plxdc1, which was isolated in a screen for genes upregulated in human colorectal tumour endothelium (and originally named tumour endothelial marker 7, TEM7." (PMID 21283688, 2011).
diabetic retinopathy (1 paper, 2021). "We observed the species R. intestinalis associated with rs79499638 (P = 3.81 × 10−8) and rs760646544 (a insertion of CTGTT, P = 1.75 × 10−8) near PLXDC2 (related to nidogen-1 measurement and diabetic retinopathy in GWAS catalog)." (PMID 33563976, 2021).
dyslipidemia (1 paper, 2017). "Subsequently, a congenic strain with the substitution of only 17q12.3 identified Camk1d and Plxdc2 as candidate genes for hypertension and dyslipidemia in the LH strain." (PMID 28792545, 2017).
gastritis (1 paper, 2020). Inflammation of the stomach. "Of note, many uninfected Plxdc2-deficient mice displayed mild spontaneous gastritis (data not shown), which points towards the role of Plxdc2 in maintaining tissue homeostasis." (PMID 32661418, 2020).
laryngeal carcinoma (1 paper, 2018). Carcinoma that arises from the laryngeal epithelium. "Increased methylation levels of promoters of TOP2A (DNA topoisomerase II alpha), PLXDC2 (plexin domain containing 2), ETNK2 (ethanolamine kinase 2), GFI1 (growth factor independent 1 transcriptional repressor), and IL12B (interleukin 12B) were detected in radioresistant laryngeal cancer cells." (PMID 29439529, 2018).
lymph node metastasis (1 paper, 2025). "In the tumor (T), lymph node (N), and metastasis to distant organs (M) classification, serum PLXDC2 levels tended to increase in the presence of lymph node metastasis (N1‐2) (mean: 32.19 ng/mL) compared to the absence of lymph node metastasis (N0) (mean: 22.24 ng/mL) (p = 0.09)." (PMID 41365610, 2025).
pancreatic cancer (1 paper, 2025). "However, the role of PLXDC2 in pancreatic cancer has not been examined." (PMID 41365610, 2025).
Stroke (1 paper, 2021). Sudden impairment of blood flow to a part of the brain due to occlusion or rupture of an artery to the brain. "LAMA2, MLL4 and PLXDC2 are specifically expressed in (pre-)diabetic sera; CD99 is expressed in the sera of both healthy and (pre-)diabetic patients; and CD14, CLU and SAA2 are expressed in the sera of healthy, (pre-)diabetic and stroke subjects." (PMID 33995275, 2021).
type 2 diabetes (1 paper, 2018). "Notably, several age-downregulated genes, such as Plxdc2, Igf1, Igf2bp3, and Igf1r, and upregulated genes, such as Adam19 and Tmem163, have been linked to IGF signaling or type 2 diabetes." (PMID 30180872, 2018).
tumor (15 papers, 2011 to 2025). "One study has demonstrated that PLXDC2 is highly expressed in stromal cells and its cross-talk with tumor-associated macrophages contributes to cancer biology by inducing the EMT process." (PMID 37089864, 2023). "Plexin domain containing 2 (PLXDC2), a tumor endothelial marker, has been implicated in several cancers, but its role in PDAC remains unclear." (PMID 41365610, 2025). "Our data suggested that PLXDC2 was expressed in stromal cells and that its crosstalk with tumor-associated macrophages could contribute to cancer biology by inducing the EMT process." (PMID 34124056, 2021). "For the purpose of confirming the association of PLXDC2 expressions with the immunity microenvironmental status, the percentage of tumor infiltrating immunity subsets was assayed via CIBERSORT arithmetic, and 21 types of immunocyte profiles in GC specimens were established." (PMID 34777633, 2021). "PLXDC2 is strongly expressed in PDAC tissues with poor‐to‐moderate tumor differentiation, showing a similar expression pattern to maspin staining." (PMID 41365610, 2025). "PTEN is secreted by tumor cells via binding to TMED10 and then binds to PLXDC2 on tumor associated macrophages (TAMs) and induces inflammatory status through triggering JAK2-STAT signaling, thus contributing to the tumor suppressor function of PTEN." (PMID 40766638, 2025). "PLXDC2 upregulation was also observed in primary postradiotherapy tumor tissues collected from patients with radioresistant HNSCC, suggesting that our research findings have a strong clinical relevance." (PMID 37089864, 2023). "PLXDC2 staining was low or absence in adjacent normal tissues, but high in tumor tissues and metastatic lymph node, mainly in cytoplasm and membrane of GC cells." (PMID 35661947, 2022). "The expression of PLXDC2 protein in 170 GC specimens with tumor and adjacent normal tissues was examined by IHC." (PMID 35661947, 2022). "Both at mRNA and protein levels, the expressions of PLXDC2 were significantly elevated in tumor tissues as compared to adjacent normal counterparts." (PMID 35661947, 2022). "The proportion of high expression of PLXDC2 (PLXDC2high) defined by the optimal cutoff value of 0.138 was significantly higher in tumor tissues than in adjacent normal tissues (62.4%, 106/170 vs. 20.6%, 35/170; P = 0.001)." (PMID 35661947, 2022). "To confirm the results of IHC, we measured the expression of PLXDC2 at mRNA and protein levels in 20 and 6 pairs of fresh GC tumor and adjacent tissues by qRT-PCR and Western blotting, respectively." (PMID 35661947, 2022). "Higher PLXDC2 expression was observed in GC stromal tissues than in tumor tissues within 52 cases, the number of which is after the removal of films with poor dyeing quality." (PMID 34124056, 2021). "Plexin domain containing 2 (PLXDC2), also known as TEM7R, is a member of the tumor endothelial marker (TEM) family, which is associated with tumor-specific angiogenesis." (PMID 34124056, 2021). "An integrated gene profile and functional analysis of the proportions of tumor-infiltrating immune cells revealed that the expression of the M2 macrophages cell marker CD163 was positively correlated with PLXDC2 expression." (PMID 34124056, 2021). "The closest homolog to Plxdc2, Plxdc1 was initially identified as overexpressed in blood vessels of solid human tumors, resulting in the original terminology tumor endothelial marker 7 (TEM7, Plxdc1) and tumor endothelial marker 7 related (TEM7R, Plxdc2)." (PMID 33657166, 2021). "Plexin domain containing 2 is a vital member of the TEM family and is associated with tumor-specific angiogenesis." (PMID 34124056, 2021). "The crosstalk between PLXDC2 expressed tumor stroma and CD163 macrophages and with tumor cell’s EMT process is extricate and interesting." (PMID 34124056, 2021).